AQP4 (aquaporin 4)
Diseases named in the same sentence as AQP4 in open-access papers (continued):
Sharing a sentence is not in itself a finding about the gene and the disease.
optic neuritis (continued). "Here, we describe a 57-year-old woman with a history of diabetes mellitus and hypertension treated with telmisartan, who presented with progressive visual impairment of the left eye due to anti-aquaporin-4 antibody-positive optic neuritis." (PMID 32340132, 2020). "The remaining two participants with AQP4 antibodies experienced APS with optic neuritis (n = 1) or myelitis (n = 1) at the time of relapse." (PMID 32581992, 2020). "Even if some studies report functional and microstructural damages in MOG-Ab optic neuritis, visual recovery measured by visual acuity seems poorer in double seronegative and AQP4-Ab patients with optic neuritis." (PMID 32326965, 2020). "Whereas, several studies exist describing transsynaptic damage after optic neuritis and myelitis, the existence of global atrophy, and diffuse tissue alterations of WM and GM in AQP4-IgG seropositive NMOSD is still a matter of debate." (PMID 31258505, 2019). "In a subgroup of AQP4 antibody (AQP4-IgG) seronegative NMOSD patients as well as in patients with recurrent optic neuritis and a few patients with multiple sclerosis (MS) an antibody against myelin oligodendrocyte glycoprotein (MOG-IgG) can be detected." (PMID 31258505, 2019). "More recently, anti-AQP4 antibodies have been found also in a subset of patients with isolated transverse myelitis, patients with isolated optic neuritis and patients with NMOSD and co-existing connective tissue diseases." (PMID 32257061, 2019). "Using CBA antibodies targeting MOG have been recently identified in both children and adults with demyelination disorders including acute disseminated encephalomyelitis (ADEM), optic neuritis (ON), transverse myelitis (TM), and AQP4-seronegative NMOSD." (PMID 31212763, 2019). "Bilateral optic nerve lesions occur more commonly in MOG (and AQP4-IgG) optic neuritis than in MS optic neuritis." (PMID 31212763, 2019). "Patients presenting with ADEM-like illness who have optic neuritis or transverse myelitis should be screened for AQP4-ab." (PMID 31163654, 2019). "It is currently a matter of debate if retinal damage following optic neuritis is equally severe in AQP4-NMOSD and MOG-EM and to which extent structural retinal alterations occur in NMOSD independently of optic neuritis attacks." (PMID 30405519, 2018). "In patients with AQP4-Abs, the most frequent symptoms at onset are optic neuritis in 37-54% of the patients, and LETM in 30–47% of the patients." (PMID 30405519, 2018). "Serum antibodies (Abs) against the aquaporin-4 water channel lead to recurrent attacks of optic neuritis, myelitis and/or brainstem syndromes." (PMID 30405519, 2018). "There was one patient repeatedly positive for AQP4 in this group and he had unilateral optic neuritis, cerebral sensory manifestations, typical MS brain, and cervical spinal cord lesions in MRI with contrast enhancement." (PMID 29682349, 2018). "In optic neuritis patients, AQP4-IgG was found in 0-11.4% patients in western countries and 9 – 35.2% in Asian countries." (PMID 30258505, 2018). "In the majority of patients with NMOSD, autoantibodies (Abs) against the astrocyte aquaporin-4 (AQP4) water channel are detectable and patients typically suffer from recurrent attacks of severe optic neuritis or/and myelitis." (PMID 30405519, 2018). "All patients had ON owing to acute isolated ON (Cases 1, 3, 5, and 6), MS (Cases 2, and 4) or anti-aquaporin-4 antibody-positive optic neuritis (Case 7)." (PMID 28192497, 2017). "Limited forms of NMO, optic neuritis (ON) or transverse myelitis (TM), positive for the anti-AQP4 antibody are diagnosed as NMO spectrum disorder (NMOSD)." (PMID 28293214, 2017). "The purpose of this study was to investigate the impact of AQP4 Ab on inner retinal structure, function, and the structure−function relationships in eyes with optic neuritis." (PMID 28199381, 2017).
optic neuritis (continued). "Antibodies against myelin oligodendrocyte glycoprotein (MOG-IgG) have been detected in some patients with AQP4-IgG seronegative NMO as well as with recurrent optic neuritis, longitudinally extensive transverse myelitis, MS and SLE." (PMID 26950113, 2016). "Myelin oligodendrocyte glycoprotein antibodies (MOG-IgG) are present in a subset of aquaporin-4 (AQP4)-IgG-negative patients with optic neuritis (ON) and/or myelitis." (PMID 27802825, 2016). "Bilateral, simultaneous optic neuritis attacks are more common in patients with MOG-IgG than in those with AQP4-IgG or in seronegative ones." (PMID 26950113, 2016). "The objective of this study was to describe optic neuritis (ON)-induced neuro-axonal damage in the retina of MOG-IgG-positive patients in comparison with AQP4-IgG-positive NMOSD patients." (PMID 27802824, 2016). "If optic neuritis or transverse myelitis occurs in a patient with already diagnosed systemic autoimmune disease, AQP4-IgG assay should be carried out." (PMID 26950113, 2016). "NMO is characterized by optic neuritis, transverse myelitis, and the presence of anti-aquaporin-4 antibodies in the serum." (PMID 26106494, 2015). "In terms of clinical presentation, half of the MOG-seropositive (2/4) or AQP4-seropositive (16/31) patients and about two thirds (8/13) of the seronegative patients had an initial presentation with uni-/bilateral optic neuritis (ON)." (PMID 25889963, 2015). "Only three patients (42.8%) with relapsing optic neuritis were positive for anti-AQP4 antibody out of 7 patients." (PMID 25548676, 2014). "As our patient had optic neuritis, myelitis, MRI evidence of a contiguous spinal cord lesion of five segments in length and NMO-IgG seropositivity, she was diagnosed as having anti-aquaporin 4 antibody-positive NMO according to the diagnostic criteria for NMO." (PMID 23575376, 2013). "Anti-AQP4 antibodies have also been found in patients with isolated longitudinally extensive transverse myelitis and in patients with isolated optic neuritis, conditions which are considered limited or inaugural forms of NMO." (PMID 22719979, 2012). "When there is isolated or recurrent optic neuritis or transverse myelitis along with the presence of AQP4 antibody the patient is said to have an NMO spectrum disorder." (PMID 20182570, 2009). "After 5 months the patient had another attack of transverse myelitis, had electrophysiological findings consistent with optic neuritis, was seropositive for NMO-IgG (aquaporin-4 IgG) and thus fulfilled NMO diagnostic criteria." (PMID 19852774, 2009). "Eighty-eight patients with AQP4-Ab positive optic neuritis initiated on biologics were included." (PMID 39470886, 2025). "A previous study suggests that astrocyte damage and high expression of AQP4 antibodies may play an important role in the occurrence of optic neuritis." (PMID 41446878, 2025). "She fulfilled both the 2015 International Panel for NMO Diagnosis (IPND) criteria and the 2023 revised recommendations by the Neuromyelitis Optica Study Group (NEMOS), demonstrating AQP4-IgG seropositivity along with optic neuritis and corresponding T2-hyperintense lesions on optic nerve MRI." (PMID 40698091, 2025). "The present study demonstrates that initiation of the biologic agents satralizumab in patients with NMOSD demonstrates the possibility of reducing the dose of or discontinuing steroids after initiation, and was highly effective in preventing relapse of AQP4-Ab positive optic neuritis." (PMID 39470886, 2025). "Similarly, in humans, optic neuritis has been described as a rare sequela of COVID-19 but appears to be more related to antibodies against myelin oligodendrocyte glycoprotein and aquaporin-4." (PMID 40733579, 2025). "In addition, the antibody-mediated nature of astrocytopathy in NMO-driven optic neuritis is evidenced by antibody and complement deposition on astrocytic endfeet, where AQP4 is expressed, within parenchymal lesions." (PMID 41583430, 2025).
optic neuritis (continued). "In pediatric patients, an important probability of developing thyroid dysfunction was found post-treatment with surgery, chemotherapy, and radiotherapy; moreover, abnormalities in thyroid function were found in patients with AQP4 antibody–seropositive optic neuritis." (PMID 38476871, 2024). "Although the long-term recovery of the implicit times of the VEPs is not fully known as in MS eyes with optic neuritis and anti-AQP4 antibody-positive optic neuritis, the prolonged implicit times of the pVEPs persisted even after the clinical recovery from the optic neuritis in our case." (PMID 39184699, 2024). "Bilateral optic neuritis involving the chiasma, focal lesions in areas like the area postrema, midbrain, or diencephalon and “pencil-thin” subependymal enhancement are characteristic of AQP4 + NMOSD." (PMID 38473365, 2024). "NMOSD, associated with AQP4 antibodies, typically presents with more severe optic neuritis and spinal cord involvement but does not involve MOG antibodies." (PMID 38903369, 2024). "However, its application in demyelinating diseases, especially in the context of AQP4 and MOG antibody-associated optic neuritis pathogenesis, is yet to be fully explored." (PMID 39238786, 2024). "The dataset GSE226808, encompassing peripheral blood RNA-sequencing samples from patients with aquaporin-4 positive optic neuritis (AQP4-ON), myelin oligodendrocyte glycoprotein (MOG) antibody positive optic neuritis (MOG-ON), and healthy controls, was utilized in this study." (PMID 39238786, 2024). "In China, 35–50% of optic neuritis patients are AQP4 antibody seropositive." (PMID 37840923, 2023). "Sequential or concomitant attacks of transverse myelitis and optic neuritis, with contiguous spinal cord MRI lesions extending over three or more vertebral segments with the presence of anti-aquaporin 4 antibodies (AQ4 Ab) not only define NMOSD but also differentiate it from multiple sclerosis." (PMID 36681831, 2023). "Sequential or concomitant attacks of transverse myelitis and optic neuritis, with contiguous spinal cord lesions on magnetic resonance imaging (MRI) extending over three or more vertebral segments, with the presence of anti-aquaporin 4 antibodies (AQ4 Ab) distinguish NMOSD from multiple sclerosis." (PMID 36681831, 2023). "They proposed a new classification of autoimmune optic neuritis, including MS-associated optic neuritis (MS-ON), AQP4 antibody–associated optic neuritis (AQP4-ON), MOG antibody–associated optic neuritis (MOG-ON), and CRMP5 antibody–associated optic neuritis (CRMP5-ON)." (PMID 37448746, 2023). "Autoantibodies against AQP4 water channels on astrocytes were also found, and they are associated with NMOSD, another autoimmune CNS inflammatory disorder, characterized by recurrent attacks of severe optic neuritis and/or myelitis." (PMID 37104301, 2023). "NMO is an autoimmune disease of the CNS in which binding of anti-aquaporin-4 (AQP4) autoantibodies (NMO-IgG) to astrocytes causes complement-dependent cytotoxicity (CDC) and inflammation causing demyelinating lesions cause optic neuritis and transverse myelitis." (PMID 37569559, 2023). "She presented 1 year before her mother’s AQP4-IgG positive NMOSD diagnosis with 7 months history of bilateral visual loss of rapid onset, with gadolinium-enhancing optic nerves on Brain and orbit MRI, in keeping with bilateral optic neuritis." (PMID 37667215, 2023). "Here, we report a case of radiologically isolated optic neuritis in a child who was found to have AQP4-Ab, despite not fulfilling 2015 NMOSD diagnostic criteria." (PMID 35332817, 2022). "AQP4 Abs have been associated with neuro-myelitis optica spectrum disorder (NMOSD), which manifests as severe attacks of optic neuritis, longitudinally extensive myelitis, diencephalon, and brainstem involvement, including area postrema syndrome (nausea, vomiting, incoercible hiccup)." (PMID 34997443, 2022).
optic neuritis (continued). "Another possibility is that the pRNFL and mGCIPL becomes “bottomed out” at around 50-60 μm and therefore OCT may not capture the greater extent of optic nerve damage that may occur in AQP4-IgG+NMOSD optic neuritis compare to MOGAD." (PMID 35785363, 2022). "We present three cases with serum AQP4‐IgG who developed optic neuritis after minor traumas." (PMID 33591639, 2021). "Of note, NMOSD encompasses a group of syndromes that share optic neuritis and/or acute myelitis as their manifestation, but the patients can be seropositive or seronegative for AQP4-IgG, supporting the heterogeneity of the conditions included in NMOSD, and particularly in AQP4-IgG-negative NMOSD." (PMID 34354581, 2021). "Diagnosis of NMOSD is done by aquaporin-4 antibody (AQP4) in patients with optic neuritis." (PMID 34484845, 2021). "Optic neuritis in anti-MOG syndrome exhibits some peculiar features that may distinguish it from optic neuritis in AQP4-IgG NMOSD and MS." (PMID 31212763, 2019). "MOG-Abs can be detected in NMOSD with AQP4-Ab seronegative, recurrent optic neuritis, transverse myelitis, multiphasic acute disseminated encephalomyelitis, and combined central and peripheral demyelination (CCPD) syndromes; a proportion of these patients will develop a relapsing type of disease." (PMID 31061727, 2019). "One take-home message from this report is that AQP4 autoantibodies found in NMOSD might be triggered by an increase in AQP4 MPs, which may precede the neuropsychiatric symptoms related to optic neuritis." (PMID 30696485, 2019). "Characteristics of MOG-IgG-associated diseases include optic neuritis as a major symptom, good response to steroid, absence of serum AQP4-Ab, and steroid-dependent relapse or disease exacerbation." (PMID 30382857, 2018). "Despite the worse outcomes in the German group, comparison of recovery rates from optic neuritis and/or transverse myelitis attacks to previously published rates for AQP4-NMOSD showed an improved recovery rate (more complete and less partial/no recovery), but less than observed with MS." (PMID 29064441, 2017). "Interestingly, AQP4-IgG seropositive patients with recurrent optic neuritis (ON) or the first episode of LETM are particularly at high risk of relapse." (PMID 26950113, 2016). "According to several studies, the occurrence of optic neuritis and/or transverse myelitis in AQP4-IgG seropositive patients with systemic autoimmune disease (e.g., SS or SLE) should not be regarded as a vasculitic complication of a systemic disorder, but as the coexistence of these two diseases." (PMID 26950113, 2016). "The low female-to-male ratio, the absence of coexisting autoimmune diseases (e.g. MG), and the predominance of LETM (with a low incidence of optic neuritis) in the anti-AQP1-seropositive NMOsd patients are similar to the characteristics of anti-AQP4-seronegative NMOsd." (PMID 24086369, 2013). "Optic neuritis, comparison of clinical features according to the patient's AQP4-Ab serostatus." (PMID 22260418, 2012). "Nonetheless, this heterogeneity in clinical and MRI activity, combined with the inclusion of NMOSD AQP4 + patients presenting with either optic neuritis or myelitis, may have introduced variability that could affect CSF cytokine profiles and their relationship with neurological disability." (PMID 41057549, 2025). "In 2007, the term NMOSD was introduced to include anti-AQP4 antibody-positive patients with limited or inaugural forms of NMO (e.g., first-attack longitudinally extensive transverse myelitis (LETM) or recurrent or bilateral optic neuritis) who were at high risk for future attacks." (PMID 40018473, 2025). "Still, it's associated with relapsing and bilateral optic neuritis, brainstorm encephalitis, and acute disseminated encephalomyelitis (ADEM); MOGAD is more common in children than adults; 60% have CSF pleocytosis and can mimic the NMOSD syndrome seen in patients with the anti-AQP4 antibody." (PMID 38807813, 2024).
optic neuritis (continued). "Optic neuritis (ON) is a common feature of inflammatory demyelinating diseases (IDDs) such as multiple sclerosis (MS), aquaporin 4-antibody neuromyelitis optica spectrum disorder (AQP4 + NMOSD) and myelin oligodendrocyte glycoprotein antibody–associated disease (MOGAD)." (PMID 38646958, 2024). "Second, although we only included patients whose last attack was transverse myelitis, most patients with RRMS or AQP4 + NMOSD had experienced optic neuritis or demyelinating brain attacks earlier during their disease course, which may have affected their levels of serum biomarkers." (PMID 36894677, 2023). "LETM is often considered to be within the spectrum of NMO spectrum disorder (NMO-SD), which typically presents with bilateral optic neuritis, and has a strong association with aquaporin-4 (AQP4) antibodies (though not required), with MOG seropositivity being less common." (PMID 35399911, 2022). "The diagnosis of NMO requires the presence of optic neuritis, myelitis, spinal cord lesions involving three or more segments by magnetic resonance imaging (MRI), brain MRI not meeting the criteria of multiple sclerosis, and/or seropositive aquaporin-4 antibodies (AQP4-Abs)." (PMID 34598735, 2021). "It is believed that an increase in T cell activity depends on the G allele and may result in higher CNS inflammation frequency, which in turn facilitates access of aquaporin 4 (AQP4), a water carrier membrane antibody, into the CNS and ultimately leads to the spread of optic neuritis." (PMID 29736281, 2018). "Importantly, the presentation of bilateral simultaneous optic neuritis or optic neuritis with transverse myelitis is common in MOG-NMOSD and greater than that seen for AQP4-NMOSD, which invites a careful search of the diagnostic criteria, as previously reported." (PMID 29064441, 2017). "Anti-AQP4 seropositivity was found in 38/48 (79.2%) with NMO, 12/21 (57.1%) with brain involvement at high risk for NMOSD, 12/15 (80%) with transverse myelitis (i.e., 11/15 with relapsing transverse myelitis and one with monophasic transverse myelitis), and 3/7 (42.8%) with relapsing optic neuritis." (PMID 25548676, 2014). "Regarding the disease type of AQP4-Ab positive NMOSD, 38 patients manifested optic neuritis alone, and 50 patients had myelitis concurrent with optic neuritis." (PMID 39470886, 2025). "In the present study, we investigated the usage status of three biologic agents in Japan: satralizumab, eculizumab and inebilizumab, in patients with AQP4-Ab positive NMOSD, focusing on those with newly diagnosed or relapsed optic neuritis." (PMID 39470886, 2025). "Both AQP4-NMOSD and MOGAD frequently manifest as optic neuritis (ON), which can result in significant neuronal damage and blindness." (PMID 40495001, 2025). "Among these, 18 (69.2%) were female, and 6 (23.1%) had previous CNS-IDD diagnoses, including 3 cases of acute myelitis, 2 cases of optic neuritis, and 1 case of NMOSD with AQP4-IgG." (PMID 38228919, 2024). "This included four patients diagnosed with RRMS, three with NMOSD with AQP4-IgG, and one with a single TDL and a history of bilateral optic neuritis." (PMID 38228919, 2024). "In this study, we applied Weighted Gene Co-expression Network Analysis (WGCNA) to an in-depth transcriptomic analysis of peripheral blood samples from patients with AQP4 antibody and MOG antibody-positive optic neuritis." (PMID 39238786, 2024). "With the progress of molecular biology and bioinformatics, current understandings of AQP4-related and MOG-related optic neuritis have transcended the realm of autoantibody discovery, advancing into the molecular mechanisms and the realm of epigenetics." (PMID 39238786, 2024). "In this study, we utilized Weighted Gene Co-expression Network Analysis (WGCNA) to investigate the transcriptomic profiles of peripheral blood samples from patients with AQP4-ON and MOG-positive optic neuritis (MOG-ON), compared to healthy controls." (PMID 39238786, 2024).